ZNF217 (zinc finger protein 217)
Diseases named in the same sentence as ZNF217 in open-access papers (continued):
Sharing a sentence is not in itself a finding about the gene and the disease.
breast carcinoma (continued). "The established role of ZNF217 as an oncogene combined with these findings strongly support miR-503 as a candidate tumor suppressor in breast cancer." (PMID 27539783, 2016). "Among the genes repressed by estrogen stimulation is the oncogene ZNF217, which has been shown to enhance proliferation in ovarian and breast cancer." (PMID 27539783, 2016). "Specifically, silencing of ZNF217 results in reduced proliferation in several breast cancer cell lines (including MCF-7), and overexpression of ZNF217 increases proliferation in the same cell lines as well as in xenograft tumors." (PMID 27539783, 2016). "Taking together these compelling observations with the etiological relevance of ZNF217 to breast cancer, we selected ZNF217 as a potential target of miR-503 for further investigation." (PMID 27539783, 2016). "Overexpression of ZNF217 promoted mammosphere formation and increased metastasis in an orthotopic mouse model of breast cancer." (PMID 27590511, 2016). "As a novel zinc finger transcription factor, ZNF217 was initially identified as a tumorigenic stimulator in breast carcinoma and was frequently amplified in diverse malignancies." (PMID 27007163, 2016). "ZNF217 is a transcriptional regulator that works together with ERα to amplify the estrogen response in breast cancer." (PMID 27539783, 2016). "ZNF217 enrichment has been found in the promoters for Snail1 and Snail2 genes in human breast cancer cell lines and tumors, and the promoter of the E-cadherin gene is a direct target for ZNF217." (PMID 26431164, 2015). "Investigation of ZNF217 expression would thus allow the stratification of breast cancer patients into outcome-dependent subclasses." (PMID 26431164, 2015). "Altogether, these data suggest that in breast cancer, ZNF217 mRNA expression is both a novel and powerful biomarker for poor prognosis and a prognostic predictor of patient outcome in response to chemotherapy." (PMID 26431164, 2015). "The first evidence of this came from the observation that ZNF217 is (directly or indirectly) an ERα target gene, as 17β-estradiol exposure led to ZNF217 mRNA deregulated expression in ER+ breast cancer cells." (PMID 26431164, 2015). "In breast cancer cells, ZNF217-induced overexpression of ErbB2 and ErbB3 proteins is paired with increased phospho-FAK levels." (PMID 26431164, 2015). "Triciribine overcomes in vitro ZNF217-induced doxorubicin resistance in breast cancer cells, and in mice experiments is more effective in inhibiting tumor growth of ZNF217-overexpressing cells than control tumors." (PMID 26431164, 2015). "Six genes have been reported to contribute to about 44% of driver mutations in breast cancer (copy number increase or amplicons): MYC, FGFR1 (Chromosome 8); CCND1 (Chromosome 11); HER2, TOP2A (Chromosome 17); and ZNF217 (Chromosome 20)." (PMID 26008969, 2015). "ZNF 217 is a candidate oncogene in breast cancer, and overexpression of ZNF217 was found to promote migration and invasion of breast cancer cells in vitro and stimulate the development of spontaneous lung or lymph node metastasis in vivo." (PMID 25871474, 2015). "We further used pooled samples to carry out DNA FISH for six genes previously reported to contribute to driver mutations in breast cancer: MYC, FGFR1, CCND1, HER2, TOP2A, and ZNF217." (PMID 26008969, 2015). "More recently, subcellular fractionation of MCF-7 breast cancer cells revealed the presence of endogenous ZNF217 protein predominantly in the nuclear fractions, but also in the cytoplasmic fraction." (PMID 26431164, 2015). "A model for ZNF217-driven deleterious functions in ER+ breast cancer cells involving interference with and enhancement of ERα signaling and its related mitogenic downstream events, at least via the direct genomic activity of ERα, is proposed." (PMID 26431164, 2015). "All these results proved lnc-ATB functions as a ceRNA by regulating ZEB1 and ZNF217 expression in breast cancer." (PMID 25871474, 2015).
breast carcinoma (continued). "Ectopic expression of ZNF217 conferred both doxorubicin and paclitaxel resistance in breast cancer cells, and conversely, ZNF217 silencing increased doxorubicin or paclitaxel sensitivity." (PMID 26431164, 2015). "The Aurora-A kinase inhibitor III was efficient in reversing paclitaxel resistance in ZNF217-overexpressing breast cancer cells in vitro." (PMID 26431164, 2015). "Ectopic expression of ZNF217 conferred aggressiveness and tamoxifen endocrine therapy resistance to ER+ breast cancer cells, while ZNF217 silencing restored tamoxifen sensitivity in resistant breast cancer cells." (PMID 26431164, 2015). "Compelling data indicate a specific behavior of ZNF217 in an ER+ context of breast cancers and a close interplay between ZNF217 and ERα signaling." (PMID 26431164, 2015). "Earlier work using ChIP-chip tiling arrays for the 5 kb DNA region surrounding the transcriptional start site (TSS) identified ZNF217 regulatory gene targets in the embryonal carcinoma cell line, Ntera2, and the breast cancer cell line MCF7." (PMID 24962896, 2014). "In the current study we employed an integrative genomics approach to uncover the mechanisms of ZNF217 target gene regulation in breast cancer cells." (PMID 24962896, 2014). "Data-mining of expression data from breast cancer patients correlates ZNF217 with reduced overall survival." (PMID 24962896, 2014). "Our findings contribute to the genome-wide potential of ZNF217 in the hierarchy of ERα-mediated regulation by multiple transcription factors and provide a possible mechanism by which ZNF217 contributes to poor prognosis in breast cancer patients." (PMID 24962896, 2014). "This occupancy and motif analysis highlights a significant interaction between ZNF217 and alternative breast cancer transcription regulators." (PMID 24962896, 2014). "Using a combination of RNA- and ChIP-seq techniques in MCF7 breast cancer cells, we focused on identifying genes that were regulated by ZNF217 DNA binding." (PMID 24962896, 2014). "To elucidate the regulatory function of ZNF217 in breast cancer, we performed genome-wide chromatin mapping of ZNF217 by ChIP-seq using the ER+ HER2- MCF7 cell line." (PMID 24962896, 2014). "Our current studies demonstrate a high correlation between ZNF217 and ERα expression in breast cancer cell lines and breast tumor tissue, yet the precise role of ZNF217 in ER+ breast cancer is not fully understood." (PMID 24962896, 2014). "In support of a transcriptional role for ZNF217 in aberrant ERα signaling, we identified a ZNF217-ERα gene signature with ontological classification that aligns with multiple breast cancer studies." (PMID 24962896, 2014). "The identification of the ZNF217-ER gene signature aligning with multiple breast cancer studies further supports a transcriptional role for ZNF217 in aberrant ERα signaling." (PMID 24962896, 2014). "We previously found that high ZNF217 expression is a prognostic indicator in general as well as in ER+HER2+LN− patients with breast cancer correlating with shorter overall, disease-specific, and relapse-free survival." (PMID 24962896, 2014). "Our findings suggest that ZNF217 overexpression in ER+, Luminal A, or other subtypes of breast cancer will identify a subset of patients with worse prognosis who will benefit from more aggressive or alternative therapy." (PMID 24962896, 2014). "Another gene on 20q, ZNF217 was shown to be a marker for poor breast cancer prognostis and its overexpression promotes epithelial-mesenchymal transition (EMT) and invasion." (PMID 24344117, 2013). "Amplification was observed over cancer genes previously implicated in breast cancer development including ERBB2, CCND1, MYC, MDM2, ZNF217, and ZNF703 and a homozygous deletion involving MAP2K4 was identified." (PMID 22608084, 2012). "ZNF217 is a candidate oncogene located at 20q13, a chromosomal region frequently amplified in breast cancers." (PMID 21059223, 2010).
breast carcinoma (continued). "In this study, we investigated the functional consequences of aberrant ZNF217 expression on breast cancer cell behavior." (PMID 21059223, 2010). "Conversely, siRNA-mediated silencing of ZNF217 expression in MCF7 breast cancer cells, which possess high endogenous levels of ZNF217, led to decreased cell proliferation and increased sensitivity to paclitaxel." (PMID 21059223, 2010). "We also newly demonstrated that treatment with a potent Aurora-A kinase inhibitor is able to reverse paclitaxel resistance in ZNF217-overexpressing breast cancer cells." (PMID 21059223, 2010). "With the aim of selecting relevant breast cancer cell lines to study the impact of ZNF217 expression on breast cancer cell phenotype, we analyzed ZNF217 mRNA and ZNF217 protein levels in MCF7 and MDA-MB-231 breast cancer cells." (PMID 21059223, 2010). "Only ZNF217, a putative driver of 20q amplification in breast cancer shows over-expression in cancer samples with this amplification." (PMID 19419571, 2009). "Included in this region were STK15, which has recently been suggested to be a candidate low-penetrance tumor susceptibility gene in breast cancer and MYBL2, which has been shown to be overexpressed along with STK15 and ZNF217 in prostate cancer." (PMID 17428335, 2007). "The zinc finger protein 217 (ZNF217) gene, in the amplicon on chromosome 20q13.2, encodes a Krupple-like transcription factor and is a candidate oncogene expressed in 20%–30% of primary human breast cancers, with overexpression correlating with poor prognosis." (PMID 36873929, 2023). "In ER+ breast cancer, ZNF217 worked as a positive enhancer of ER." (PMID 35494043, 2022). "High ZNF217 mRNA levels in primary breast tumors are also of bad prognosis and associated with shorter relapse free survival (RFS) and metastasis development, with the most discriminatory prognostic power observed in Luminal breast cancers." (PMID 34277402, 2021). "Besides, it was reported that miR-503 suppressed cell proliferation of breast cancer MCF-7 cells by directly targeting oncogene ZNF217, acting as a tumor suppressor miRNA." (PMID 33817293, 2021). "Taking advantage of the specificity of primer pair 2 and primer pair 3, we thus aimed at investigating in a pilot study the prognostic value of ZNF217-WT (E3-E4) and ZNF217-ΔE4 (E3-E5) mRNA expression levels, alone or in combination, in the molecular subtypes of breast cancer." (PMID 34277402, 2021). "Altogether, these data demonstrate that overexpression of ZNF217-ΔE4 in breast cancer cells enhances their aggressiveness and that the impact of ZNF217-ΔE4 expression on the phenotype of breast cancer cells seems to be at least as or more efficient than that of ZNF217-WT." (PMID 34277402, 2021). "Strikingly, the ectopic overexpression of ZNF217-ΔE4 in breast cancer cells led to: (i) a more aggressive phenotype, similar to that previously observed with ZNF217-WT; (ii) increased expression of endogenous ZNF217-WT; and (iii) decreased DNA methylation on key CpG sites within the ZNF217 gene." (PMID 34277402, 2021). "Our study thus indicates that the ZNF217-ΔE4 isoform triggers, directly or indirectly, a poor phenotype in breast cancer cells that may involve dysregulated ZNF217-WT expression levels." (PMID 34277402, 2021). "ZNF217 has been found to be an indicator of bone metastasis in breast cancer." (PMID 32742190, 2020). "In breast cancer, the studies of this loop mainly focused on mesenchymal-like characteristics involving different pathways or factors, such as the H-Ras signaling pathway, as well as the transcription factor zinc finger protein 217 (ZNF217)." (PMID 32014049, 2020). "Moreover, EPB41L4A-AS2 expression was also found to be downregulated in MDA-MB-231 breast cancer cells overexpressing ZNF217 in the GEO dataset GSE35511." (PMID 30764831, 2019).
breast carcinoma (continued). "According to the Gene Expression Omnibus (GEO), the expression levels of C6orf141 could be silenced in breast cancer cell lines with ZNF217 (Zinc finger protein 217) overexpression." (PMID 30872783, 2019). "Indeed, treatment of MDA-MB-231 breast cancer cells overexpressing ZNF217 with specific BMP inhibitors (one of which being LDN-193189) led to impaired ZNF217-dependent cell migration and cell invasion and impeded chemotaxis to the bone." (PMID 31275146, 2019). "The researchers have also reported that the exposure of breast cancer cells to hypoxia induces zinc finger protein 217 (ZNF217)-dependent inhibition of m6A methylation of mRNAs encoding NANOG and Kruppel-like factor 4 (KLF4), which is another pluripotency factor that mediates BCSC speciation." (PMID 29587823, 2018). "ZNF217 is a candidate oncogene with a wide variety of deleterious functions in breast cancer." (PMID 30740056, 2018). "ZNF217 has previously been shown by our work and others to be a critical component of estrogen signaling and an important prognostic factor for breast cancer." (PMID 30483308, 2018). "ZNF217 is expressed at the highest levels in breast cancer patients with the worst prognosis." (PMID 29312549, 2017). "High expression of ZNF217 is correlated with increased breast cancer mortality." (PMID 27590511, 2016). "Several studies have demonstrated that ZNF217 promotes breast cancer progression." (PMID 27590511, 2016). "Among all cohorts on ZNF217 expression, breast carcinoma was the most frequent cancer type (n = 4)." (PMID 27007163, 2016). "Based these data, we hypothesized that ZNF217 may also inhibit m6A modification of pluripotency factor mRNAs in hypoxic breast cancer cells to promote the BCSC phenotype." (PMID 27590511, 2016). "In addition to regulating breast cancer progression, later studies also identified that ZNF217 plays a critical role in other cancers, such as ovarian cancer, esophagus cancer and prostate cancer." (PMID 27768596, 2016). "LncRNA-ATB also regulates ZNF217 expression via miR-200c in keloid fibroblasts and breast cancer." (PMID 27768596, 2016). "Besides, ZNF217 enrichment has been found in the promoter for Snail1 and Snail2 genes in human breast cancer, and the promoter of the E-cadherin gene is a direct target for ZNF217." (PMID 27768596, 2016). "Increased ZNF217 expression is correlated with patient mortality in breast cancer and glioma." (PMID 27590511, 2016). "Furthermore, ZNF217 has a demonstrated role in promoting proliferation in several models of breast cancer." (PMID 27539783, 2016). "ZNF217 also sensitized breast cancer cells to heregulin, the growth factor ligand for ErbB3." (PMID 26431164, 2015). "ZNF217 was initially found to be amplified in breast cancer and considered to work as an oncogene." (PMID 25658832, 2015). "Interestingly, both nuclear and cytoplasmic ZNF217 staining has been used to define an IHC ZNF217 index in a breast cancer study." (PMID 26431164, 2015). "Overexpression of ZNF217 in normal primary mammary epithelial cells or breast cancer cells increased the formation of mammospheres displaying self-renewal capacity and was associated with repression of an adult stem cell expression signature that is also found downregulated in cancer." (PMID 26431164, 2015). "ZNF217 expression was deregulated in endocrine therapy-resistant breast cancer cells." (PMID 26431164, 2015). "Indeed, in vitro overexpression of ZNF217 promoted cell proliferation in ovarian and breast cancer cells, whereas silencing of ZNF217 reduced it in prostate, colorectal, ovarian and breast cancer cells." (PMID 26431164, 2015). "On the other hand, lnc-ATB could enlarge its effect on trastuzumab resistance and EMT of breast cancer by lnc-ATB/ZNF217/TGF-β signaling pathway." (PMID 25871474, 2015). "In peripheral blood cells, lack of methylation at the ZNF217 locus, predicting breast cancer risk, was associated with ERα bioactivity in the corresponding serum." (PMID 26431164, 2015).
breast carcinoma (continued). "Finally, high ZNF217 mRNA (univariate analysis, p = 0.02, p = 0.011, p = 0.047, p = 0.035) or protein levels (p = 0.05) in human ER+ primary breast cancer tumors were predictors of earlier relapse under endocrine therapy only." (PMID 26431164, 2015). "Taken together previous studies and our results, we tend to confirm lnc-ATB could augment its effects on trastuzumab resistance in breast cancer by lnc-ATB/ZNF217/TGF-β positive feedback." (PMID 25871474, 2015). "In breast tumors, the methylation status at the ZNF217 gene promoter correlated with ZNF217 gene-expression levels while in peripheral blood cells, lack of methylation at the ZNF217 locus predicted breast cancer risk (p = 0.006)." (PMID 26431164, 2015). "Future studies will investigate whether ZNF217 expression contributes to aberrant ERalpha regulatory events in ER+ breast cancer and hormone resistance." (PMID 24962896, 2014). "An important step in understanding the molecular role of ZNF217 in breast cancer is to gain a more complete understanding of the mechanisms of genome-wide gene regulation by ZNF217 in breast cancer cells, including the involvement of cooperating transcriptional partners." (PMID 24962896, 2014). "We provide evidence that stable overexpression of ZNF217 in MDA-MB-231 breast cancer cells conferred resistance to paclitaxel, stimulated cell proliferation in vitro associated with aberrant expression of several cyclins, and increased tumor growth in mouse xenograft models." (PMID 21059223, 2010). "We have also found that high expression levels of ZNF217 in MDA-MB-231 breast cancer cells promote strong resistance (~10-fold) to the microtubule-stabilizing molecule paclitaxel, while no resistance to the nucleoside analogue gemcitabine is concomitantly developed." (PMID 21059223, 2010). "Most importantly, our data suggest that clinical strategies counteracting ZNF217-mediated effects, either by targeting ZNF217 directly and/or by targeting its possible key-mediators like Aurora-A, would be a valuable approach for the management of breast cancer." (PMID 21059223, 2010). "However, it is intriguing that even the relatively small numbers of putative mutations are enriched for zinc finger genes, including the known breast cancer oncogene ZNF217." (PMID 18364049, 2008). "In conclusion, our data highlight that assessing the expression levels of ZNF217-WT and ZNF217-ΔE4 isoforms may serve as a novel prognostic biomarker allowing a better stratification of breast cancers with good prognosis and helping clinicians in therapeutic decisions." (PMID 34277402, 2021). "This is the first pilot prospective study conducted in the neoadjuvant setting to relate ZNF217 expression levels with treatment efficacy, thus suggesting that aside from its prognostic value in luminal breast cancers, ZNF217 expression may also be predictive of response to ET." (PMID 30740056, 2018). "Furthermore, CHIP-Seq in breast cancer cells indicated that CREB1 was the target gene of ZNF217 and two binding sites in the promoter region of CREB1 could be recognized by ZNF21719." (PMID 28607476, 2017). "A detailed mechanistic analysis of the contribution of ZNF217 to therapeutic resistance combined with pre-clinical modeling will inform the design of the best treatment plan to kill these cells, thereby reducing mortality in breast cancer patients with aggressive disease." (PMID 29312549, 2017). "ZNF217 and ErbB3 expression levels showed significant correlation in human breast tumors, and ectopic ZNF217 expression induced ErbB3 protein overexpression in normal human mammary epithelial cells (HMECs) and in breast cancer cell lines (paired with increased ErbB2 expression)." (PMID 26431164, 2015). "Therefore Aurora-A is certainly part of the mechanism by which ZNF217 controls resistance to paclitaxel, and the use of a potent Aurora-A inhibitor could be sufficient to reverse ZNF217-mediated paclitaxel resistance in MDA-MB-231 breast cancer cells." (PMID 21059223, 2010).